TNF (tumor necrosis factor)
Diseases named in the same sentence as TNF in open-access papers (continued):
Sharing a sentence is not in itself a finding about the gene and the disease.
migraine (continued). "Moreover, migraine patients exhibit altered levels of circulating CD14, TNF-α, and MIP-1, with increased serum CD14 concentrations and decreased TNF-α expression in monocytes during the interictal period." (PMID 39407099, 2024). "Measurement of the PACAP as well as other inflammatory substances, like PGE2 and PGI2, interleukin-6 (IL-6), tumor necrosis factor (TNF-α) and the c-Fos gene, all of which are typically upregulated in both clinical and preclinical migraine studies, have also been utilized." (PMID 38481473, 2024). "Research conducted on cultured trigeminal neurons suggests that migraine treatment strategies can inhibit CGRP transcription and curtail its release, while tumor necrosis factor alpha (TNF-α) may stimulate the transcription of this peptide." (PMID 37755358, 2023). "Additionally, supporting a role for neurogenic inflammation in migraineurs, elevated levels of plasmatic IL-1β, prostaglandin E2, tumor necrosis factor-α (TNF-α), IL-6, or nitrite were observed during migraine attacks." (PMID 38062355, 2023). "Moreover, another recent study confirmed that the inflammatory cytokines, including IL-1β, TNF-α, and IL-6, significant decreased after EA treatment at GB20 and GB34 in a migraine model." (PMID 37190506, 2023). "Similarly, systemic deactivation of SFKs reduces cortical spreading depression (CSD), a migraine with aura model, and CSD-induced cerebral cortical inflammatory cytokines interleukin 1 beta (IL-1β) and tumor necrosis factor alpha (TNFα) gene expression." (PMID 36359895, 2022). "Although changes in TNF-α and other cytokines can be confirmed, it is not clear as to their significance in migraine pathology." (PMID 35954288, 2022). "A 2021 study measured cytokine levels in the blood in migraine patients and healthy controls and discovered that TNF-α was elevated, but IL1-β was not compared to controls." (PMID 35432179, 2022). "One could also consider whether the recipe in the IS should be revised, adding some inflammatory mediators that have been observed in the serum of migraine patients like IL-6, CGRP and TNF-α." (PMID 35954288, 2022). "In 2018, we showed that serum levels of CRP and tumor necrosis factor alpha (TNF-α) did not correlate with frequency of migraine attacks." (PMID 34991456, 2022). "Migraine patients had elevated levels of interleukin-4 (IL4), TGF-β, TNF-α and interferon gamma." (PMID 35432179, 2022). "Interleukin (IL)-1β, IL-6, IL-10, and tumor necrosis factor (TNF)-α levels are elevated in the blood during or early in the migraine pain period compared to the non-migraine pain period." (PMID 34444772, 2021). "We found that the blood serum levels of only TNF-α, but not IL-6, were significantly higher in migraine patients than in the controls." (PMID 32019484, 2020). "It is reported that TNF level changes in migraine patients without aura while it is normal in patients with chronic type tension headache." (PMID 32231773, 2019). "Considering the very high prevalence of migraine, several hundred-thousand migraine patients must have received TNF-α antibody but there are no reports on any prevention of migraine attacks, not even in case-reports." (PMID 31870279, 2019). "Significantly increased ictal IL-1β, IL-6 and TNF-α serum concentrations were measured in migraine patients with/without aura compared to post-ictal (after 1 week treatment) and healthy subjects not clearly indicative for a predictive value." (PMID 30795781, 2019). "Furthermore, TNF-α can stimulate transcription of calcitonin gene-related peptide (CGRP), which plays a pivotal role in the pathophysiology of migraine." (PMID 26098763, 2015). "Despite their plausible associations with migraine, this meta-analysis revealed no general associations between the TNF –308G>A or NOS3 +894G>T polymorphism and migraine risk." (PMID 26098763, 2015).
migraine (continued). "While LPS is not a model tool to induce migraine pain, it can induce expression and release of TNFα, which is known to have a role in trigeminal ganglia sensitisation." (PMID 23326332, 2013). "On the other hand, a surge in extracellular TNFα might serve to increase TRPV1 receptor activity and, thus, perhaps amplify peripheral nociceptive transduction which is thought to be important for migraine pain." (PMID 23577145, 2013). "Its role in migraine has been postulated based on reports of TNF-alpha concentration changes in serum and urine among migraineurs, as well as findings that TNF-alpha can stimulate transcription of calcitonin gene-related peptide (CGRP), which is pivotal in migraine pathophysiology." (PMID 22072275, 2012). "TNF alpha, IL-6, IL1 beta and IL10 were found to be increased during migraine attacks." (PMID 21331754, 2011). "While IL-4 itself is not typically measured in migraine natural history studies, a higher IL-4/TNF ratio, for instance, could hypothetically indicate a less inflammatory milieu and potentially less risk of chronification." (PMID 41377228, 2025). "Moreover, molecular docking results demonstrated that these core components have a strong affinity with multiple target proteins such as PTGS2, PPARG, BCL2, CASP3, TNF, and ESR1, suggesting that ginkgo seeds exert their therapeutic effects on migraines through multiple targets and pathways." (PMID 41009787, 2025). "Importantly, none of the trials specifically administered a cytokine-blocking drug (no trials of anti-TNF biologics or similar were found in migraine)." (PMID 41377228, 2025). "Migraine sufferers (with and without aura) and obese patients have elevated plasma or serum concentrations of many inflammatory markers, including IL-1β, IL-6, IL-8, TNF-α, and C-reactive protein levels." (PMID 39600744, 2024). "We have identified higher levels of IL-6, IL-8 and TNF-α in patients with migraine compared to healthy controls, higher levels of TGF-β and TNF-α in tension-type headache compared to healthy controls, and higher levels of IL-1β during attacks of migraine compared to the interictal period." (PMID 37016284, 2023). "Our finding of increased TNF-α in tension-type headache, similarly to migraine, may suggest either an overlap in pathophysiology between migraine and tension-type headache, or it may be a non-specific finding secondary to the chronic daily headache disorder." (PMID 37016284, 2023). "In term of treatments, using TNF-α antibodies did not alleviate symptoms in migraine patients and arguably triggered migraines, challenging the view of inflammation as an initiator of debilitating migraine symptoms." (PMID 36908624, 2023). "Thus, the elevated levels of interferon-gamma and TNF-α, which regulate the synthesis of CGRP, could account for the link between migraine and celiac disease." (PMID 36168375, 2022). "This suggests that preventing TNF-α inflammation is not a viable anti-migraine target." (PMID 31870279, 2019). "Studies eligible for this meta-analysis were searched in the PubMed, Embase, and CNKI by using the keywords “tumor necrosis factor”, “TNF”, “252A>G”, “rs909253”, “polymorphism”, “polymorphisms”, “variant”, “SNP”, combined with “migraine” or “migraine with aura (MA)” or “migraine without aura (MO)”." (PMID 24959879, 2014). "In contrast, if an intervention improved headaches without affecting a cytokine (probiotics improving migraines without TNF change, or vitamin D/probiotic combo with no CRP change), it suggests that particular marker might not be a key driver of chronification in that context." (PMID 41377228, 2025). "Therefore, antagonists of TNF-a and TRPV1 may be effective in stress-related migraine." (PMID 38802819, 2024). "Our findings appear to support the hypothesis that the TNF –308G>A polymorphism may act as a genetic susceptibility factor for migraine among non-Caucasians and that the NOS3 +894G>T polymorphism may modulate the risk of migraine among non-Caucasians." (PMID 26098763, 2015).
migraine (continued). "Although gut microbiota profiles differed significantly between M + G and M + noG patients, plasma levels of migraine markers (CGRP and PGE2) and inflammatory indices (IL-1β, IL-6, NF-κB, TNF-α) did not." (PMID 41454664, 2026). "A recent study in patients with migraine without aura showed that PACAP-38 infusion elevated the plasma levels of VIP, prolactin, S100 calcium binding protein, and thyroid-stimulating hormone but not CGRP and tumor necrosis factor-α." (PMID 29442286, 2018).
glaucoma (203 papers, 2008 to 2026). Increased pressure in the eyeball due to obstruction of the outflow of aqueous humor. "TNF α is a critical pro-inflammatory cytokine implicated in the apoptotic death of RGCs in glaucoma." (PMID 39951447, 2025). "Because microglia are implicated in many neurodegenerative diseases, including glaucoma, we used N9 microglia to elucidate the mechanisms associated with TNFα-mediated metabolic remodeling with potential implications for glaucoma." (PMID 39184151, 2024). "The marked increase in TNF-α expression as a result of proinflammatory imbalance in glaucoma is associated with RGCs loss." (PMID 38333055, 2024). "In a mouse model of glaucoma, a rapid upregulation in TNF-alpha was caused by microglial activation and retinal ganglion cell loss." (PMID 37511830, 2023). "Of note, an essential aspect of TNF that should be considered is the relationship between the systemic levels of TNF and the risk of developing or monitoring the progression of glaucoma." (PMID 35651608, 2022). "This is the first review article focusing on glaucoma in relation to the associations of TNF and its receptors." (PMID 35651608, 2022). "The presence of a TNF-308 G/A polymorphism which leads to greater transcriptional activation has been demonstrated to be significantly higher in primary open-angle glaucoma and pseudoexfoliative glaucoma in specific populations." (PMID 35986368, 2022). "In a clinical study using an enzyme-linked immunosorbent assay, TNF-α was detected more frequently in glaucoma patients (17.8%) compared to cataract patients (5.0%)." (PMID 36079162, 2022). "Although some studies have shown that increased IOP activates TRPV4, it is not well-established that TRPV4 activation in Müller cells is linked with TNF-α production and glaucoma pathology." (PMID 35563594, 2022). "Other authors similarly showed that microglia are highly activated in the optic nerve head in human eyes with glaucoma, in association with the abundant expression of TNF-α, TGF-β and matrix metalloproteinases." (PMID 35844208, 2022). "Studies have reported that polymorphism and increment of TNF-α in the vitreous body, retina and optic nerve are associated with glaucoma." (PMID 35778750, 2022). "On the other hand, the TNFR phenotypes’ roles in glaucoma revealed TNF gene polymorphisms that either increase or reduce the risk of glaucoma." (PMID 35651608, 2022). "Proinflammatory cytokine TNFα has also been shown to cause NOX2-dependent ROS production in microglia and TNFα has indeed been detected in aqueous humour of glaucoma patients." (PMID 33557289, 2021). "Among these were several pathways previously implicated in glaucoma, such as neurotrophin signaling, fluid sheer stress, TNF signaling, and apoptosis." (PMID 34156425, 2021). "NLY01, used to block the induction of inflammatory astrocytes by inhibiting the release of IL-1α, TNF-α and C1q from microglia, was successfully used in studies of PD and glaucoma-associated neurodegeneration to ameliorate disease severity." (PMID 34539348, 2021). "Support for this notion was the elevation of TNFα in the aqueous humor of glaucoma patients and rodent models of glaucoma, correlating with the worsening of RGC loss." (PMID 32117239, 2020). "TNF-α is found in the optic nerve in glaucoma patients and also Fas ligand (FasL), a proapoptotic protein, both being implicated in glaucoma pathogenesis." (PMID 33613418, 2020). "In a C57BL/6 mouse model of glaucoma, increased levels of TNF-α were demonstrated to cause microglial activation, loss of oligodendrocytes in the optic nerve, and loss of RGCs in an irradiation-induced murine model of ocular hypertension (OHT)." (PMID 33014446, 2020). "Each of these cytokines has been associated with glaucoma pathogenesis in other studies; for example, TNFα is released by retinal glia and leads to RGC axon degeneration through the upregulation of Ca++-permeable AMPA receptors." (PMID 30424795, 2018).
glaucoma (continued). "In glaucoma, microglial activation and an inflammatory response involving Toll-like receptors (TLRs), complement molecules and cytokines, such as TNFα and IL-1β, is associated with secondary phase of the disease." (PMID 25301432, 2014). "It is now believed that inflammation plays an important role in the development and progression of glaucoma, and several reports have linked TNF-α to glaucoma injury." (PMID 24146536, 2013). "This meta-analysis was performed to clarify the association between tumor necrosis factor alpha (TNF-α) gene polymorphisms and open angle glaucoma (OAG) risks, and the association between the TNF-α level in aqueous humor (AH) and the risks of glaucoma." (PMID 23559847, 2013). "Several functional polymorphisms in the promoter region of the TNF-α gene have been identified, and have been related to the risks of glaucoma." (PMID 23559847, 2013). "In that study, eight studies investigating the association between the TNF-α −308G/A polymorphism and the risks of glaucoma were included; those were included in the current study, in which five additional newly published studies were included." (PMID 23559847, 2013). "Several publications have evaluated the association between the TNF promoter polymorphisms and glaucoma risk." (PMID 22509108, 2012). "To date, several publications have evaluated the association between TNF-α promoter polymorphisms and glaucoma risk." (PMID 22509108, 2012). "Tumor necrosis factor (TNF)-α is a proinflamatory cytokine that has been implicated in various neurodegenerative disorders including glaucoma." (PMID 23157966, 2012). "The current study confirms and extends previous findings linking retinal ganglion cell (RGC) loss in glaucoma to TNF-α." (PMID 22802951, 2012). "Several mechanisms are implicated in retinal ganglion cell death in glaucoma including direct effect on retinal ganglion cells, activation of glial cells to produce cytotoxic molecules like TNFα, alteration in trabecular meshwork, autoimmunity etc." (PMID 21408173, 2011). "A glaucoma-associated mutant of optineurin, E50K, showed significantly more inhibition of TNFα-induced NF-κB activation in HeLa cells." (PMID 19340308, 2009). "The TNF-α –308 G>A polymorphism has also been recently implicated in the pathogenesis of primary open-angle glaucoma." (PMID 19279689, 2009). "The distribution of the TNF-α G/A polymorphism was in accordance with the Hardy–Weinberg equilibrium in the PEX patients with glaucoma and the controls (p=0.657, p=0.218, respectively)." (PMID 18852869, 2008). "The distribution of TNF-α G/A polymorphism between PEX glaucoma patients and controls was significantly different from each other (p=0.019)." (PMID 18852869, 2008). "TNF-α and another proapoptotic protein, FasL, have been implicated in the pathogenesis of glaucoma." (PMID 38562304, 2024). "TNF-α has been widely associated with glaucoma and RGC loss." (PMID 39150567, 2024). "Altered levels of different miRNAs in AH samples from glaucoma patients may regulate target genes linked to apoptosis and inflammation, such as Bcl-2, caspase-3, IL-6, IL-8, TNF, and nuclear factor κB (NFκB)." (PMID 38333055, 2024). "TNF-alpha levels are related to retinal ganglion cell apoptosis, and the higher level in the AH of glaucoma patients may be associated with increased outflow resistance." (PMID 37511830, 2023). "Although TNF-associated glaucoma has been well documented, its receptors are severely understudied." (PMID 35651608, 2022). "A number of molecular pathways have been suggested as major regulators of neuroinflammation that may be implicated in glaucoma pathogenesis, including the complement cascade, Toll-like signaling, and tumor necrosis factor α pathway." (PMID 35075201, 2022).